MSLN (mesothelin)
Description:
Membrane-anchored forms may play a role in cellular adhesion. Megakaryocyte-potentiating factor (MPF) potentiates megakaryocyte colony formation in vitro.
Synonyms: MPF; CAK1; SMRP
Tractability: Antibody: a drug acting on it is in phase 2 or 3 trials; its Gene Ontology location is reachable by antibodies, with high confidence; UniProt places it where antibodies can reach, with medium confidence; UniProt predicts a signal peptide or a membrane-spanning region; the Human Protein Atlas places it where antibodies can reach. PROTAC: ubiquitination databases record sites on it. Other modalities: a drug acting on it is in phase 2 or 3 trials.
Gene: Protein-coding gene on chromosome 16 (760,734 to 768,866, forward strand). Ensembl gene ENSG00000102854.
Subcellular location: Cell membrane; Golgi apparatus; Secreted (Megakaryocyte-potentiating factor); Secreted (Isoform 5)
Subcellular location (Human Protein Atlas): Plasma membrane; Vesicles
Pathways (Reactome):
Metabolism of proteins: Post-translational modification: synthesis of GPI-anchored proteins; Post-translational protein phosphorylation; Regulation of Insulin-like Growth Factor (IGF) transport and uptake by Insulin-like Growth Factor Binding Proteins (IGFBPs)
Gene Ontology:
Molecular function: protein binding
Biological process: cell adhesion; cell-matrix adhesion
Cellular component: plasma membrane; cell surface; endoplasmic reticulum lumen; extracellular region; membrane; Golgi apparatus
Genetic constraint (gnomAD): Loss-of-function variants: 82 observed, 66.77 expected, observed/expected ratio (o/e) 1.23, 90% interval 1.03 to 1.48. The synonymous counts are far from expectation, so gnomAD's model fits this gene poorly and the ratio says little. Missense variants: 1,005 observed, 814.34 expected, observed/expected ratio (o/e) 1.23, 90% interval 1.17 to 1.3. Synonymous variants: 456 observed, 372.83 expected, observed/expected ratio (o/e) 1.22, 90% interval 1.13 to 1.32.
Homologues: Orthologues: macaque MSLN (83% identical), chimpanzee MSLN (79% identical), guinea pig MSLN (61% identical), mouse Msln (58% identical), rat Msln (57% identical), tropical clawed frog msln (30% identical). Paralogues in human: MSLNL (23% identical), OTOA (17% identical), STRC (16% identical).
Diseases named in the same sentence as MSLN in open-access papers:
MSLN is named in the same sentence as 194 diseases in open-access papers, as found by Europe PMC text mining. Sharing a sentence is not in itself a finding about the gene and the disease. The quoted sentences say what the papers report.
ovarian carcinoma (282 papers, 2004 to 2026). A malignant neoplasm originating from the surface ovarian epithelium. "Elevated MSLN expression has been associated with advanced clinical stage of the disease, platinum resistance, and poorer survival outcomes, particularly in ovarian cancer patients, although prognostic findings remain inconsistent." (PMID 42279275, 2026). "The amplification of JUNB was associated with a worse outcome in ovarian cancer patients, while the gene MSLN, prevalent in C3 FN1+ TCs, was previously thought to have a role in the peritoneal dissemination of ovarian TCs." (PMID 40612060, 2025). "Poor patient outcomes and relapse-free survival have been associated with MSLN expression in gastric, pancreatic and ovarian cancer, cholangiocarcinoma, breast cancer, endometrial cancer and lung cancer." (PMID 40227616, 2025). "Some studies have shown that MSLN is associated with poor prognosis in patients with ovarian cancer." (PMID 41400642, 2025). "Although the oncogenic role of MSLN has been widely recognized, its specific roles and associations with prognosis differ among various cancers such as pancreatic cancer, ovarian cancer, and mesothelioma." (PMID 41400642, 2025). "MSLN was discovered in 1992 by Chang and collaborators as an antigen associated with ovarian cancer and other malignancies." (PMID 41335396, 2025). "Thereby, we revealed a signature of three TOP genes encoding proteins within our dataset (CORO1B, LAMP2, MSLN), which were differentially expressed in ovarian cancer patients compared to healthy individuals." (PMID 41551606, 2025). "MSLN is a surface protein associated with apoptosis resistance, invasion, and metastasis in various tumors including mesothelioma, pancreatic cancer, ovarian cancer, and lung cancer." (PMID 41154636, 2025). "The cell surface glycoprotein encoded by MSLN is closely associated with the development of pancreatic and ovarian cancers, and it serves as a target antigen for CAR-T therapy." (PMID 39519383, 2024). "Given the high specificity and selectivity of MUC16 and MSLN as diagnostic markers, they have very high potential as theranostic targets to diagnose, treat, and monitor ovarian cancers." (PMID 40836974, 2024). "Higher levels of MSLN expression in pancreatic cancer cells are associated with increased cell proliferation, similar to what has been observed in ovarian cancer, lung cancer and malignant mesothelioma." (PMID 38628720, 2024). "Altogether, our study demonstrates the enhanced therapeutic potential of MSLN-CAR T cells expressing a mutated CD3ζ chain containing a single ITAM for the treatment of ovarian cancer." (PMID 36746513, 2023). "have shown that MSLN is involved in various pathways, thus causing poor prognosis for ovarian cancer (OC) patients." (PMID 36713571, 2022). "For ovarian carcinomas, various tumor-associated antigens, such as Mucin-16 and Mesothelin, have been described." (PMID 35565389, 2022). "We further used the ROC curve to evaluate the diagnostic value of MSLN in ovarian cancer, and the results showed that MSLN had high accuracy (AUC > 0.9) in predicting ovarian cancer." (PMID 35692779, 2022). "We further evaluated the diagnostic value of MSLN and found it was associated with poor overall survival in ovarian cancer." (PMID 35692779, 2022). "High MSLN expression in human cancer cell lines, including ovarian cancer, has been associated with tumor cell adhesion, increased tumor burden, invasion through mesothelial cells, dissemination within the peritoneal cavity and chemoresistance." (PMID 34830322, 2021). "Although MSLN and mesothelial cells have been implicated in ovarian cancer progression in several studies, the potential contribution of host MSLN expression to the metastatic success of ovarian cancer has not yet been addressed." (PMID 34830322, 2021).
ovarian carcinoma (continued). "Here, we found that high MSLN expression levels are associated with the presence of ascites and shorter progression-free survival in epithelial ovarian cancer (EOC) patients and that primary and matched peritoneal metastasis of HGSC share MSLN overexpression." (PMID 32612258, 2020). "The aim of this review is to discuss the characteristics of MSLN in ovarian carcinoma, especially focusing on its diagnostic and therapeutic perspectives." (PMID 32983962, 2020). "Using several genetically engineered ovarian cancer cell lines, resulting in loss or gain of function, we found that MSLN increased cell survival in suspension and invasion of tumor cells through the mesothelial cell layer in vitro." (PMID 32612258, 2020). "MSLN in the sera of patients with ovarian cancer and mesothelioma has been identified as diagnostic biomarker." (PMID 31222072, 2019). "Currently, there are many new diagnostic markers for ovarian cancer, such as mesothelin, TRIM44 and BCRA1 methylation." (PMID 31767040, 2019). "Mesothelin is a protein, which the membrane form was confirmed to be associated with a few tumors—pancreatic adenocarcinoma but also ovarian cancer or mesothelioma." (PMID 30791358, 2019). "Cell surface glycoprotein mesothelin is highly expressed in ovarian cancer and its expression has been associated with poor prognosis." (PMID 30344925, 2018). "Epithelial ovarian cancer is associated with high levels of mesothelin expression, and therefore, mesothelin is an attractive candidate target for the treatment of this disease." (PMID 30344925, 2018). "Mesothelin is a tumor-associated antigen that is highly expressed in many tumors, including ovarian cancer, lung adenocarcinoma, and pancreatic adenocarcinoma." (PMID 29568387, 2018). "Mesothelial cells, expressing mesothelin, line the peritoneal wall and all the organs of the peritoneal cavity that is susceptible to ovarian cancer metastasis." (PMID 30134520, 2018). "N-ERC/mesothelin is a soluble protein and has been reported to be a diagnostic serum marker of mesothelioma and ovarian cancer." (PMID 24146039, 2014). "Folate receptor alpha (FOLR1, a membrane-bound molecule) and mesothelin (MSLN, a glycosyl-phosphatidylinositol-linked cell surface antigen) that are upregulated in ovarian carcinoma are also upregulated in serous EC more frequently than in endometrioid EC." (PMID 23819113, 2013). "Mesothelin has been reported to be a tumour-associated marker in several types of human cancers, including ovarian carcinomas and adenocarcinomas arising from the pancreatico-biliary tract, endometrium, and lungs." (PMID 23034174, 2012). "In next step, treatment of ovarian cancer cells (OVca429) with a lentivirus expressing anti-mesothelin microRNA resulted in significant loss of viability, invasiveness, and morphological alterations." (PMID 22485139, 2012). "Our study presenting mesothelin expression in ovarian carcinomas provides new evidence that a higher mesothelin expression is associated with chemoresistance in patients and shorter patient survival." (PMID 19293794, 2009). "Mesothelin has been reported as a tumour-associated marker in several types of human cancers, including ovarian carcinomas and adenocarcinomas arising from the pancreatico-biliary tract, endometrium, and lungs." (PMID 19293794, 2009). "Mesothelin is overexpressed in ovarian cancer and associated with poor prognosis." (PMID 40940995, 2025). "Our work demonstrates the central role of HLA-DR-restricted peptide presentation of the tumor antigen Mesothelin and of CD4+ T-cell responses for tumor immune surveillance, and underlines Mesothelin as a prime target antigen for novel immunotherapeutic approaches for ovarian carcinoma patients." (PMID 35565389, 2022). "Urinary mesothelin is also a good diagnostic marker for ovarian cancer." (PMID 36741380, 2022).
ovarian carcinoma (continued). "Furthermore, MSLN has been identified as a potential tumor-associated marker in approximately 70% of ovarian cancers." (PMID 34830322, 2021). "MSLN, a tumor-associated antigen, is a clinically validated target for immunotherapy and other treatment strategies for PC, mesothelioma, and ovarian cancer, including immunotoxins, vaccines, chimeric monoclonal Abs, Ab-drug conjugates, and chimeric antigen receptor (CAR) T-cell therapy." (PMID 34577541, 2021). "Mesothelin expression appears to drive tumor growth and metastasis and is negatively associated with survival in ovarian cancer, which indicates it could be a therapeutic target." (PMID 31320999, 2019). "Mesothelin is a tumor-associated antigen that is overexpressed on tumor cell membranes in a variety of human cancers, including mesothelioma, pancreatic cancer, ovarian cancer, and lung adenocarcinomas." (PMID 29568387, 2018). "In order to evaluate the value of MSLN in the prognosis of ovarian cancer patients, we analyzed the association of MSLN and the overall survival (OS) under different histologic subtype, clinical stages, and grades of ovarian cancer through an online website Kaplan-Meier Plotter." (PMID 35692779, 2022). "Expression of mesothelin increases substantially during malignant transformation, in particular, that associated with pancreatic cancer, mesothelioma, lung cancer, pancreatic cancer, breast cancer, ovarian cancer, endometrial cancer and cervical adenocarcinoma." (PMID 36618922, 2022). "These remarkable findings demonstrated that MSLN is a very promising target for ovarian cancer treatment using CAR NK cell therapy." (PMID 40227616, 2025). "RC88 is an investigational ADC that targets mesothelin and is currently being evaluated in clinical trials for various cancers, including ovarian cancer." (PMID 41347223, 2025). "MSLN shows significant overexpression in multiple malignancies, including ovarian cancer, mesothelioma, pancreatic adenocarcinoma, and non-small cell lung cancer, and MSLN is expressed at low levels in normal tissues." (PMID 40792273, 2025). "Another study looked at QCM detection of mesothelin, which is a protein that can be found on ovarian cancer cells." (PMID 40277517, 2025). "Analogous to observations in ovarian cancer, the role of MSLN as a prognostic marker in gastric cancer remains incompletely elucidated, warranting more studies to verify its clinical utility in this malignancy." (PMID 41400642, 2025). "The role of MSLN(+)CTCs in the treatment and prognosis of ovarian cancer patients should be further investigated in the future." (PMID 40792273, 2025). "Originally identified in pancreatic cancer, CanScript has been reported to play a key role in other malignancies as well, such as mesothelioma and ovarian cancer, where it strongly enhances MSLN expression." (PMID 41335396, 2025). "MSLN targeting is in particular, associated with CA125/MUC16, which offers the potential to improve lung, pancreatic, colon and ovarian cancer detection as well as therapeutic strategies." (PMID 40227616, 2025). "Zhang’s team devised MSLN-targeted CAR-NK cells, which demonstrated robust and specific cytotoxicity against MSLN-positive human ovarian cancer cell lines, namely, OVCAR-3 and SKOV3." (PMID 40705122, 2025). "MSLN is an immunogenic glycoprotein highly expressed in ovarian cancer, non-small cell lung cancer (NSCLC), and mesothelioma." (PMID 41226368, 2025). "Mesothelin is a membrane-bound surface glycoprotein that is highly expressed in ovarian cancer, pancreatic adenocarcinoma, mesothelioma, and several other malignancies." (PMID 40417700, 2025). "In a phase I/II trial evaluating gavocabtagene autoleucel, a T-cell receptor (TCR) fusion construct targeting MSLN, patients with MSLN-expressing solid tumors, including mesothelioma and ovarian cancer, demonstrated encouraging antitumor responses." (PMID 39805063, 2025).
ovarian carcinoma (continued). "Mesothelin is a tumor differentiation antigen that is expressed in most ovarian epithelial cancers and is an emerging biomarker for OC." (PMID 40277517, 2025). "Mesothelin (MSLN), for example, is a cell surface glycoprotein present on many malignant tumours, including lung, pancreatic, and ovarian cancer." (PMID 40943226, 2025). "Anti-mesothelin ADCs represent an emerging therapeutic approach for treating mesothelin-expressing tumors, including ovarian cancer." (PMID 41347223, 2025). "So far, 64Cu‐labelled mesothelin antibodies have been tested in mouse models of ovarian cancer and a total of four patients with ovarian cancer." (PMID 40923371, 2025). "Studies have demonstrated that mesothelin-targeted CAR-NK cells effectively eliminate mesothelin-positive ovarian cancer cells." (PMID 40260240, 2025). "A few clinical studies (NCT05568680, NCT03799913, NCT04503980) are underway to investigate mesothelin-targeted CAR T-cells in patients with advanced ovarian cancer." (PMID 40940995, 2025). "DMOT4039A is another anti-mesothelin ADC under investigation for its potential in treating ovarian cancer and other solid tumors." (PMID 41347223, 2025). "MSLN- and CD19-CAR NK cells have been employed to evaluate the therapeutic efficacy of CAR-modified NK cells targeting MSLN in ovarian cancer." (PMID 40227616, 2025). "Currently, several monoclonal antibodies (e.g., amatuximab) and antibody–drug conjugates (e.g., anetumab ravtansine) targeting MSLN are being investigated in preclinical and clinical trials, particularly for mesothelioma and ovarian cancer." (PMID 40563707, 2025). "In recent years, MSLN has received widespread attention as a potential prognostic indicator for ovarian cancer." (PMID 41400642, 2025). "This study represents the investigation incorporating mesothelin, an ovarian cancer-specific target, into circulating tumor cell identification for differentiating benign and malignant ovarian masses." (PMID 40792273, 2025). "Previous studies have utilized multiantibody-modified magnetic nanoparticles targeting MSLN, EpCAM, and N-cadherin for the isolation and molecular analysis of circulating tumor cells in epithelial ovarian cancer." (PMID 40792273, 2025). "Overall, although MSLN plays an important role in ovarian cancer, its utility as a prognostic marker remains unestablished and warrants further investigation to validate its prognostic value." (PMID 41400642, 2025). "CAR-NK therapies targeting ovarian cancer, with MSLN-, CD24- and αFR-targeted CAR-NK cells demonstrating strong preclinical efficacy, show promise." (PMID 40705122, 2025). "Key targets for CAR-NK cells include mesothelin and folate receptor alpha (FRα), both of which are overexpressed in ovarian cancer." (PMID 40260240, 2025). "Although clinical trials of mesothelin-targeting agents have primarily focused on pleural mesothelioma, ovarian cancer, and pancreatic cancer, preliminary efficacy has been observed with certain mesothelin-targeting ADCs in cervical cancer patients." (PMID 40697656, 2025). "Our findings showcase the potential for CAR T-cell therapies based on mesothelin that can treat ovarian cancer and other MUC16-positive malignancies." (PMID 38637885, 2024). "They found that just one normal case, 1/24 (4.2%), had a mild expression, compared to 84.9% (56/66) of the ovarian cancer samples showing strong expression of MSLN." (PMID 38694508, 2024). "Mesothelin (MSLN) is a membrane-bound surface glycoprotein that has emerged as a promising candidate for ovarian cancer diagnosis." (PMID 40836974, 2024). "Most importantly, a monoclonal anti-MSLN antibody has been successfully applied to suppress tumor growth in a murine ovarian cancer xenograft model." (PMID 40836974, 2024). "MSLN was positively correlated with migration and invasion of pancreatic cancer cells, as described in ovarian cancer cells." (PMID 38628720, 2024).